VEGFA (vascular endothelial growth factor A)
Diseases named in the same sentence as VEGFA in open-access papers (continued):
Sharing a sentence is not in itself a finding about the gene and the disease.
lung carcinoma (continued). "Through negatively regulating VEGFA, tubeimoside-1 inactivates ERK signaling, consequently hindering cell viability and metastasis of lung cancer cells." (PMID 33066509, 2020). "The expression and clinical significance of VEGFA and ANGPT2 have been investigated in lung cancer, but the results are controversial." (PMID 31892982, 2020). "For example, TAMs isolated from 96 primary lung cancer tissues displayed the elevated level of cathepsin K, COX-2, MMP-9, PDGF-B, uPA, VEGFA, and HGF." (PMID 33194645, 2020). "It has been previously reported that TLR4-induced autophagy activation promoted migration and invasion of lung cancer by induction of chemokines and immunosuppressive factors including CCL2, CCL20, IL-6, VEGFA, and MMP2." (PMID 32384667, 2020). "VEGFA and EGFR are common therapeutic targets for lung cancer and closely related to the survival and prognosis of lung cancer patients." (PMID 32148531, 2020). "In lung cancer, co-expression of NOTCH-1 and vascular endothelial growth factor-A predicts poor survival." (PMID 32655137, 2020). "Cobalt chloride (CoCl2) was adopted to mimic a hypoxic microenvironment and western blot was used to detect the expression of hypoxia inducible factor-1α (HIF-1α), VEGFA and ANGPT2 in lung cancer cell lines." (PMID 31892982, 2020). "Corrective therapy to improve vascularization in the tumor by inhibiting vascular endothelial growth factor A (VEGF-A) signaling has been clinically beneficial in glioblastoma, lung cancer and age-related macular degeneration." (PMID 31134013, 2019). "In this study, we demonstrate that VEGFA, ANGPT2, and PLAT are up-regulated in ADAM9-expressing lung cancer cells." (PMID 29118335, 2017). "MiR-497 retards lung cancer cell growth or invasion by targeting CCNE1, VEGFA, whereas miR-497 does so by targeting SSRP1 in HCC." (PMID 28624790, 2017). "The observation in animal models is consistent with the clinical dataset analyses that poor outcomes in lung cancer patients with simultaneous high expression of ADAM9 and VEGFA or of ADAM9 and ANGPT2." (PMID 29118335, 2017). "It has been reported by other groups that IL-6, VEGFA and PDGFDB were significantly up-regulated in macrophages isolated from tissues of human lung cancer and glioblastoma." (PMID 24194900, 2013). "The gene expression level of VEGFA, PGF, and their receptors FLT1 and KDR as well as MMP-2 and the inhibitors TIMP-1 and TIMP-2 was higher in samples from lung cancer resections compared to pneumothorax and transplant biopsy samples." (PMID 22593690, 2012). "Immunohistochemical studies showed lower expression levels of VEGFA and MMP-2 in lung cancer resections compared to pneumothorax and transplant biopsies, while in contrast TIMP-1 and KDR expression was higher in lung cancer." (PMID 22593690, 2012). "There was weaker staining of MMP-2 and VEGFA in the transplant biopsies, and the levels of PGF were found to be lower in lung cancer resections." (PMID 22593690, 2012). "The expression of VEGFA and MMP-2 was lower in lung cancer resections compared to pneumothorax and the transplant biopsy." (PMID 22593690, 2012). "All groups had similar expression levels for most of the proteins analysed except TIMP-1 which was higher in the lung cancer resection, MMP-2 which was higher in lung transplant biopsy and VEGFA, which was elevated in pneumothorax samples." (PMID 22593690, 2012). "Despite the high gene expression levels of VEGFA, PGF, FLT1, KDR, MMP-2, TIMP-1, and TIMP-2, only KDR and TIMP-1 were high at the protein level in the lung cancer resections." (PMID 22593690, 2012).
lung carcinoma (continued). "In PM2.5-induced lung cancer, circCDR1as specifically binds to splicing factor 1 rich in serine/arginine (SRSF1), affecting SRSF1's splicing of VEGFA mRNA and ultimately inhibiting lung cancer cell apoptosis, thereby promoting the development of PM2.5-induced lung cancer." (PMID 40290118, 2025). "Furthermore, a recent study indicated that ADAMTS8 inhibits the progression of lung cancer by suppressing the key angiogenesis factor, VEGFA (vascular endothelial growth factor A)." (PMID 40650042, 2025). "YTHDC2 was shown to form complexes with eukaryotic translation initiation factor 4 gamma 1 (eIF4GI) and bind to the m6A methylation site of the vascular endothelial growth factor A (VEGFA) 5’UTR, thereby promoting its translation and accelerating lung cancer angiogenesis." (PMID 38790013, 2024). "To explore the effect of VEGFA on METTL3 expression in lung cancer cells, we next added recombinant VEGFA to DMEM/F12, or added VEGFA-neutralizing antibody to CAF-CM, and then used them to culture lung cancer cells." (PMID 37056933, 2023). "Western blot analyses revealed that the protein expression of AKT1, IL6, VEGFA, MMP9 in lung tissue of COPD and lung cancer was significantly increased in the model group and hesperetin could dose-dependently prevent these protein expressions (P < 0.01)." (PMID 34262419, 2021). "Further study indicated that vascular endothelial growth factor A (VEGFA) was a novel target of miR-101-3p, and CAFs-derived VEGFA mediated the effect of miR-101-3p on migration and invasion of lung cancer cells, demonstrated by using recombinant VEGFA and VEGFA neutralizing antibody." (PMID 34977016, 2021). "Moreover, the roles of VEGFA in EMT process and metastasis-related genes of lung cancer cells were also investigated." (PMID 34977016, 2021). "While VEGFA was just parallel with HIF-1α in lung cancer tissues (r= 0.420, P<0.001), not in lung cancer cell lines (r=0.315, P=0.117)." (PMID 31892982, 2020). "The clinical significance of VEGFA and ANGPT2 in lung cancer has been reported in previous studies." (PMID 31892982, 2020). "With the exception of VEGFA, the roles of 10 genes in cell migration under hypoxia in lung cancer cells have not been characterized." (PMID 31061665, 2019). "Both VEGFA and its receptor FLT4 (VEGFR-3) were altered during splicing in lung cancers LUAD and LUSC, which might modulate angiogenesis through splicing control." (PMID 31024612, 2019). "Lastly, two clinical trials using TLR9 agonists (IMO-2055, phase II; MGN1703, phase I) have been utilized as immunomodulators for lung cancer and found possible anti-tumor efficacy, either in combination with erlotinib (EGFR inhibitor) and bevacizumab (VEGFA inhibitor) or alone (MGN1703)." (PMID 29190881, 2017). "The gene expression level of VEGFA, PGF, and their receptors FLT1 and KDR as well as MMP-2 and the inhibitors TIMP-1 and TIMP-2 was significantly higher in lung cancer specimens compared to pneumothorax samples and biopsies from lung transplant patients (P < 0.001)." (PMID 22593690, 2012).
lung carcinoma (continued). "We explored the expression of the VEGFA, VEGFC, and VEGFD proteins in lung cancer and adjacent tissues and showed that VEGFA, VEGFC, and VEGFD were substantially highly expressed in lung cancer tissues, which may be the main source of VEGF-related protein expression in TDLNs." (PMID 40693467, 2025). "Moreover, stimulation with TLR4 and TLR3 can induce the production of IL-6, CCL2/MCP-1, CCL20/MIP-3α, VEGFA (vascular endothelial growth factor A), and MMP2 known to play pivotal roles in the migration and invasion of lung cancer cells through induction of autophagy." (PMID 37443143, 2023). "AKIRIN2 is necessary for the growth and metastasis of lung cancer and liver cancer and promotes the angiogenesis of gallbladder cancer through interleukin-6 (IL-6)/signal transducer and activator of transcription 3 (STAT3)/vascular endothelial growth factor A (VEGFA)." (PMID 36059811, 2022). "Due to the importance of VEGFA in angiogenesis, we first analyzed the correlation of expression between ALKBH5 and VEGFA in lung cancer tissues using the GEPIA website and found that the expression levels of ALKBH5 were positively correlated with VEGFA in lung cancer tissues." (PMID 36376862, 2022). "Thus, to assess whether the mechanism of exercise inhibiting tumor growth and metastasis is associated with tumor angiogenesis and lymphangiogenesis, we detected the protein expression of CD105, Vascular endothelial growth factor-A (VEGFA), and VEGFC lung cancer tissues." (PMID 35371324, 2022). "Quantitative gene expression of SPP1, VEGFA, POSTN, RUNX2, CD44, and FOXO1 from lung cancer patients with and without bone metastasis normalized against healthy control." (PMID 36424413, 2022). "Unfortunately, we found that neither MICE nor HIIE reduced the expression of VEGFA and VEGFC in lung cancer tissues, indicating that neither MICE nor HIIE control proliferation and metastasis of tumor cells by angiogenesis and lymphangiogenesis in tumor tissues." (PMID 35371324, 2022). "VEGFA and ANGPT2 are the targets of anti-angiogenesis therapy, and whether the combined inhibition of ADAM9 with bispecific antibody (A2V CrossMab) against both Ang-2 and VEGF can reduce the morbidity and mortality of lung cancer brain metastasis has not been studied." (PMID 35874764, 2022).
glioblastoma (741 papers, 2000 to 2026). The most malignant astrocytic tumor (WHO grade IV). "Increased VEGFA expression is significantly associated with decreased OS in patients with glioblastoma." (PMID 40867242, 2025). "MiR-21’s association with hypoxia, VEGFA regulation, and miR-10’s potential as a therapeutic target highlight their significance in glioblastoma progression." (PMID 39063226, 2024). "In contrast, Pax6 suppresses glioblastoma cell growth by downregulating the expression of the gene encoding vascular endothelial growth factor A (VEGFA)." (PMID 34195082, 2021). "VEGFA-mediated angiogenesis has been a hallmark in glioblastoma, indicating the potential value of VEGFA-targeted treatments." (PMID 33718179, 2021). "By comparing gene expression in specimen from 22 incompletely contrast-enhancing and 30 completely contrast-enhancing untreated glioblastoma, it revealed that CE was associated with distinct transcriptome signature characterized by increased VEGFA expression." (PMID 34222002, 2021). "The use of bevacizumab (Avastin), an antiangiogenic therapy against vascular endothelial growth factor type A (VEGFA), was associated with a response rate of 25% to 35% in patients with recurrent glioblastoma and was evaluated in phase III trials in the initial and recurrent setting." (PMID 34980260, 2022). "Finally, we validated the association between LRIG3 with p-AKT, and VEGFA in patients using IHC staining of these proteins in 28 glioblastoma specimens." (PMID 33718179, 2021). "Glioblastoma like many solid tumors is associated with an aggressive and aberrant neovasculature and, in recent years, has become an important target using mAb drugs such as bevacizumab, which targets Vascular endothelial growth factor A (VEGF-A)." (PMID 31354487, 2019). "This system successfully delivered an anti-VEGFA siRNA into CXCR4+ endothelial and glioblastoma cells, reducing VEGF secretion and inhibiting endothelial cells migration, validating this strategy as a promising anti-angiogenic therapy." (PMID 40307933, 2025). "The pathology of glioblastoma is characterized by the overexpression of vascular endothelial growth factor-A (VEGF-A), prompting the development of therapies targeting the angiogenic pathway." (PMID 40444037, 2025). "Downregulation of ALKBH5 in glioblastoma cells inhibits the expression of vascular endothelial growth factor A (VEGFA) and impairs the angiogenic potential of co-cultured HUVECs." (PMID 40097417, 2025). "Beyond the two well-known AD-targeting macromolecular antibodies, bevacizumab, a vascular endothelial growth factor A (VEGF-A)-targeting monoclonal antibody approved in 2004 for metastatic colorectal cancer, was later approved to treat glioblastoma." (PMID 39861756, 2025). "The paradoxical effect of increased invasion upon induction of apoptosis has been previously reported in glioblastoma, for example, upon treatment with the anti-angiogenic drug bevacizumab targeting VEGFA." (PMID 38848215, 2024). "This study highlights the intricate feedback loop involving miR-10b, miR-21, and VEGFA in glioblastoma treatment, underscoring the necessity for personalized therapeutic strategies." (PMID 39063226, 2024). "In another study, in a group of patients with recurrent glioblastomas, higher levels of VEGFA were observed in the CC homozygote group." (PMID 38139123, 2023). "The highly vascularized nature of glioblastoma enables the tumor cells to grow and invade the surrounding tissue, and vascular endothelial growth factor-A (VEGF-A) is a critical mediator of this process." (PMID 36765787, 2023). "Another study revealed that inhibition of VEGFA prolongs the survival of patients with glioblastoma." (PMID 37852616, 2023). "In a previous study, authors implanted human A673 rhabdomyosarcoma and G55 glioblastoma multiforme cells in the nude mice, and they found anti-VEGFA treatment (human VEGFA) can decrease the density of vascular elements in the xenograft tumor region of mice." (PMID 36997943, 2023).
glioblastoma (continued). "ANGPT2 activates angiogenesis through VEGFA, normalizes tumor blood vessels, and promotes the malignant transformation of glioblastoma." (PMID 36588901, 2022). "Bevacizumab, a monoclonal antibody targeted to vascular endothelial growth factor A (VEGF-A), has been shown to offer some progression-free survival benefits in patients who develop recurrent glioblastoma." (PMID 36591531, 2022). "Subsequently, GDF15 activated the transcriptional promoter VEGFA in the human glioblastoma cell line U373 through p-MAPK1/SP1 signaling." (PMID 35280749, 2022). "Recently, it was shown that glioblastoma multiforme (GBM) cells located in the NVU in close contact with the BBB secrete EVs enriched in vascular endothelial growth factor-A (VEGF-A)." (PMID 36231071, 2022). "Bevacizumab is an antibody that binds VEGFA, prevents the formation of new blood vessels, and has therapeutic activity in recurrent Glioblastoma." (PMID 35785190, 2022). "Circulating EVs collected from glioblastoma patients clinically confirmed the elevated measures of VEGFA." (PMID 34943937, 2021). "VEGFA can be used as a prognostic biomarker for head and neck squamous cell carcinoma, esophageal squamous cell carcinoma, glioblastoma and papillary thyroid carcinoma." (PMID 34630524, 2021). "Together, these results affirmed the clinical relevance of the LRIG3/PI3K/AKT/VEGFA axis and confirmed these proteins play a vital role in the regulation of glioblastoma angiogenesis." (PMID 33718179, 2021). "Vascular endothelial growth factor-A (VEGF-A) is carried by EVs derived from glioblastoma stem-like cells, increasing vascular permeability in vivo and the angiogenic potential of human brain endothelial cells." (PMID 34616739, 2021). "VEGF has been found in EVs secreted from human platelets, glioblastoma cells, and HUVECs themselves In the current study, we found VEGFA in secreted EVs from our airway basal cell line." (PMID 33731767, 2021). "In glioblastoma, cancer cell-derived EVs carrying high levels of VEGFA have been observed to induce pro-angiogenic and pro-permeability potential in brain endothelial cells." (PMID 34943937, 2021). "VEGFA was found at either the inner or outer surface of EVs from glioblastoma stem‐like cells and EV‐VEGFA still retained its pro‐angiogenic activity." (PMID 34035882, 2021). "In fact, the mRNA levels of the human vascular endothelial growth factor A (VEGFA), known to increase vascularity in glioblastoma, were lower in the brequinar-treated group after 55 days of treatment." (PMID 33201894, 2020). "LncRNA taurine upregulated 1 (TUG1) has been validated to up-regulate vascular endothelial growth factor A (VEGFA) in promoting angiogenesis in human glioblastoma via sponging shared miR-299." (PMID 32905397, 2020). "High grade glioblastomas produce large quantities of VEGFA that stimulates the proliferation of endothelial cells leading to the development of an abnormal vasculature." (PMID 33178180, 2020). "Bevacizumab, a humanized monoclonal antibody against VEGFA, has been approved by the US Food and Drug Administration agency for use in the treatment of glioblastomas, especially for patients experiencing tumor recurrence following the standard Stupp regimen." (PMID 32382013, 2020). "More recently, EndoMT of the tumor vessels has been shown to participate in the development of resistance to anti-VEGFA therapy in glioblastoma, via alterations in platelet-derived growth factor (PDGF) signaling." (PMID 32917003, 2020). "A recent study examining EndoMT in tumor vessels associated with glioblastoma showed that activation of the PDGF pathway contributes to development of EndoMT and resistance to anti-VEGFA therapy." (PMID 32917003, 2020). "Glioblastoma tumors are highly vascularized, therefore the expression of pro-angiogenic factor VEGFA is increased." (PMID 33036421, 2020).